KRT84 (keratin 84)
Description:
Structural component of intermediate filaments in keratinizing epithelia. As a type II hair keratin, forms obligate heterodimers with type I keratins to assemble keratin intermediate filaments (By similarity). Expressed predominantly in the posterior compartment of the filiform papillae of the tongue, where it contributes to the structural integrity and mechanical resilience of specialized keratinized epithelial cells (Probable).
Synonyms: KRTHB4; Hb-4; HB4
Tractability: PROTAC: ubiquitination databases record sites on it.
Gene: Protein-coding gene on chromosome 12 (52,377,812 to 52,385,652, reverse strand). Ensembl gene ENSG00000161849.
Pathways (Reactome):
Developmental Biology: Formation of the cornified envelope; Keratinization
Gene Ontology:
Molecular function: structural constituent of cytoskeleton; structural constituent of skin epidermis
Biological process: hair follicle development; intermediate filament organization; keratinization; nail development; regulation of keratinocyte differentiation
Cellular component: extracellular exosome; keratin filament; cytosol; intermediate filament cytoskeleton
Genetic constraint (gnomAD): Loss-of-function variants: 34 observed, 44.58 expected, observed/expected ratio (o/e) 0.76, 90% interval 0.58 to 1.01. The upper end of that interval is the gene's LOEUF score, 1.01, which puts it in group 4 of 6, group 1 being the genes least tolerant of losing a copy. Missense variants: 830 observed, 741.83 expected, observed/expected ratio (o/e) 1.12, 90% interval 1.06 to 1.18. Synonymous variants: 327 observed, 297.29 expected, observed/expected ratio (o/e) 1.1, 90% interval 1 to 1.21.
Homologues: Orthologues: chimpanzee KRT84 (99% identical), macaque KRT84 (96% identical), guinea pig KRT84 (84% identical), rat Krt84 (82% identical), mouse Krt84 (82% identical), pig KRT84 (82% identical), dog KRT84 (78% identical), rabbit KRT84 (69% identical). Paralogues in human: KRT85 (53% identical), KRT83 (52% identical), KRT81 (52% identical), KRT82 (50% identical), KRT86 (50% identical), KRT5 (48% identical), KRT6A (48% identical), KRT6C (48% identical), KRT6B (48% identical), KRT75 (46% identical), KRT1 (45% identical), KRT3 (45% identical), and 56 more.
Diseases named in the same sentence as KRT84 in open-access papers:
KRT84 is named in the same sentence as 8 diseases in open-access papers, as found by Europe PMC text mining. Sharing a sentence is not in itself a finding about the gene and the disease. The quoted sentences say what the papers report.
squamous cell carcinoma (1 paper, 2019). A carcinoma arising from squamous epithelial cells. "KRT84 has been reported to be up-regulated in squamous cell carcinoma and involved in metabolic pathways." (PMID 31921296, 2019).
cancer (2 papers, 2020 to 2023). A tumor composed of atypical neoplastic, often pleomorphic cells that invade other tissues. "Other DSG3-associated cancer-related genes include upregulated OLFM4 (antiapoptotic factor), downregulated ADAMTS1 (antiangiogenic activity), downregulated KRT84 (cancer suppressor in oral SCC) and FLNC." (PMID 38067138, 2023). "Genes with known implications in cancer, such as MMP-13, KRT84, OLFM4, GJA1, AMOT and ADAMTS1, were strongly linked to DSG3 overexpression." (PMID 38067138, 2023).
tumor (2 papers, 2020 to 2023). "KRT84 has been implicated as a tumour suppressor and a good prognostic indicator for oral SCC." (PMID 38067138, 2023). "The KRT84 expression level in OSCC tumor samples was strikingly decreased compared with the paracancerous samples (P = 4.23 × 10−20)." (PMID 32181476, 2020). "Among them, KRT84 expression level in OSCC tumor tissues was obviously decreased, which was validated in HSC-3 cells." (PMID 32181476, 2020). "Immunohistochemistry showed that with the increase in OSCC tumor stage, KRT84 protein level was also decreased." (PMID 32181476, 2020). "Immunohistochemistry was performed to measure the KRT84 protein levels in OSCC tumor samples from stage I to IV." (PMID 32181476, 2020). "KRT84 protein levels in OSCC tumor samples of different stages were determined by immunohistochemistry." (PMID 32181476, 2020). "In conclusion, our study showed that KRT84 expression level was down-regulated in OSCC, which presented a decreasing tendency with the increase of tumor grade, and was associated with poor prognosis." (PMID 32181476, 2020). "In the present study, we compared the gene expression levels between OSCC and paracancerous samples from TCGA, and identified KRT84 as a potential tumor suppressor." (PMID 32181476, 2020). "Then multivariate Cox regression analysis was performed on the TCGA dataset with multiple factors as variables, including gender, age, tumor stage, tumor grade, and KRT84 expression level." (PMID 32181476, 2020). "Among these DEGs, the expression level of KRT84 in the tumor tissues of OSCC was obviously lower than that in the paracancerous tissues." (PMID 32181476, 2020). "Additionally, we included the KRT84 gene in this analysis, as this gene has been reported as a potential tumour suppressor in oral SCC, with the expression level showing a decreasing tendency along with an increase in tumour grade." (PMID 38067138, 2023). "Multivariate Cox regression analysis was also conducted on the GEO dataset with factors including gender, age, tumor stage, and KRT84 expression level as variables, and the result confirmed that KRT84 was an independent prognostic factor in OSCC (HR = 1.74, P = 0.044)." (PMID 32181476, 2020). "KRT84 expression level showed decreasing tendency with the increase of tumor grade and stage." (PMID 32181476, 2020). "Moreover, the KRT84 expression level presented an obviously decreasing tendency with the increase in tumor grade." (PMID 32181476, 2020). "Elevated KRT84 mRNA as well as protein levels were confirmed by RT-qPCR and Western blot in OSCC and normal cell lines, and immunohistochemistry in OSCC tumor and paracancerous tissues." (PMID 32181476, 2020). "Survival and Cox regression analyses of the OSCC samples from TCGA revealed that patients with low KRT84 expression level had inferior OS, which was independent of multiple factors including gender, age, tumor stage, and tumor grade." (PMID 32181476, 2020). "Based on these researches, we inferred that elevated KRT84 expression level might be accompanied by strong expression of MHC class I molecules, which inhibited the tumor development and contributed to superior prognosis by enhancing the antigen processing and presentation process." (PMID 32181476, 2020).
KRT84 also shares sentences with these, for which no sentence is quoted: colorectal adenoma (2 papers); Anxiety (1); hair disease (1); infection (1); oral squamous cell carcinoma (1).